IL23A (interleukin 23 subunit alpha)
Diseases named in the same sentence as IL23A in open-access papers (continued):
Sharing a sentence is not in itself a finding about the gene and the disease.
infection (continued). "In conclusion, induction of a balanced Th1/Th17 response and production of key effector cytokines, such as IFNG, IL2, IL17, IL21, IL22 and IL23A was observed in animals that controlled infection, regardless of previous BCG-vaccination." (PMID 24505407, 2014). "In our study, the differentially regulated epithelial-derived expression of IL23A and EBI3 with their receptors upon infection with different strains of H. pylori suggests a possible biological role for these molecules either alone or in combination with other molecules." (PMID 24069393, 2013). "Interestingly, our analysis revealed a significant positive correlation between IL23A and EBI3 after infection with P1 strain only." (PMID 24069393, 2013). "Similarly, IL23A was upregulated 2.33-fold in response to infection in scarring progressors and 1.77-fold in nonprogressors." (PMID 31964744, 2020). "Likewise, fungal outgrowth was observed in the brain in absence of IL-23 at 36h and 48h post infection, while in spleen and liver the fungus was controlled to a similar extent in WT and Il23a-/- mice." (PMID 31887131, 2019). "However, after 28 days a significant decrease of proinflammatory cytokines was determined in comparison to 7 days after infection, whereas the mRNA expression level of Il-23a was not regulated regarding CVB3 infection at any time point." (PMID 28352641, 2017). "Spearman’s rho correlation table between IL23A transcript and other detected transcripts of both IL8 and IL-12-related genes after infection with different H. pylori strains regardless of cell type or duration of infection." (PMID 24069393, 2013). "On day 12 after infection, we observed selective upregulation of Il23a-Venus within the DCIR2+ cDC2s in LILP tissues while DCIR2− cDC2s and monocytes/macrophages did not express Il23a-Venus." (PMID 38180443, 2024).
tumor (47 papers, 2010 to 2025). "Other investigators demonstrated that a subunit of the IL-23 heterodimeric cytokine, encoded by the il-23a gene, significantly promoted tumor growth and shortened survival when integrated into 4T1 cells." (PMID 34093846, 2021). "Very interestingly, the expression of tumor-associated genes including vascular endothelial growth factor Vegfa, Il23a, Il23r, and matrix metalloprotease 9 (Mmp9) was almost completely suppressed by the prophylactic administration of ER-464195-01." (PMID 29773794, 2018). "We next investigated the relationship between expression of IL-23A and different clinical characteristics, and found that the level of IL-23A was associated with H. pylori infection and tumor burden." (PMID 25349535, 2014). "Our findings revealed that tumor tissues from patients undergoing neoadjuvant chemotherapy displayed higher IL-23A immunohistochemical (IHC) staining scores than those without neoadjuvant chemotherapy." (PMID 38902343, 2024). "Spearman correlation analysis demonstrated a positive correlation between the infiltration of CD8+ T lymphocytes and the expression of IL-23A in TNBC tumor tissues (Spearman r = 0.465, p = 0.0001)." (PMID 38902343, 2024). "The increase in tumor IL23A was corroborated in a validation cohort via qPCR using patient-matched tumor and non-tumor biopsies from 9 CRC patients at Vanderbilt University Medical Center." (PMID 38375204, 2023). "IL-23-a expression is substantially increased in several human cancers, leading to its tumour-promoting properties." (PMID 37761018, 2023). "We observed that IL-23A mRNA expression is higher in the primary tumor samples than in the normal tissues (p < 5.63995E-26)." (PMID 34680308, 2021). "Anti-IL-23A monoclonal antibody treatment synergistically suppressed tumor growth and metastases in combination with either targeted therapies or IL-2." (PMID 34093846, 2021). "Neo-antigen load also correlated with increased expression of IL23A, IL21, and IL17RA, all of which are players in the Th17 T cell pathway, which is implicated in both tumorigenesis as well as the anti-tumor immune response." (PMID 29487705, 2018). "We found that serum level of IL-23A was an indicator of poor prognosis in GC patients, and its expression was related to tumor volume and H.pylori infection." (PMID 25349535, 2014). "We also found upregulation of IL23A expression in neoplastic lung tissues at various stages, consistent with the reports that overexpression of IL23A was present in human tumor samples." (PMID 25176343, 2014). "We further investigated how IL23A was involved in anti-tumor cell immunity." (PMID 38902343, 2024). "We asked whether IL-23A-expressing vaccinia virus vvDD-IL-23A could promote or inhibit tumor growth." (PMID 34093846, 2021). "IL-23A can promoted GC cells growth by inducing the secretion of IL-17A in tumor microenvironment." (PMID 25349535, 2014). "IL-23A may induce the secretion of IL-17A activate IL-17A/IL-17RA/NF-κB signaling in tumor microenvironment." (PMID 25349535, 2014). "We asked whether viral delivered IL-23A could promote or suppress tumor growth." (PMID 34093846, 2021). "The expression levels of IL11, IL23A, IL27, and IL32 were significantly correlated with tumor stage." (PMID 40612864, 2025). "IL11 (p = 0.010), IL23A (p = 1.77e − 05), IL27 (p = 1e − 05) and IL32 (p = 0.001) exhibited significant correlations with tumor stage." (PMID 40612864, 2025). "In the present study, we found that the expression of IL23A was upregulated in TNBC cells by chemotherapeutics, validated by both in vitro models and resected tumor tissues from TNBC patients." (PMID 38902343, 2024). "To further study the relationship between the expression of IL23A and chemotherapy in TNBC samples, we collected resected tumor tissues from 64 TNBC patients, 27 of whom had previously received neoadjuvant chemotherapy." (PMID 38902343, 2024).
tumor (continued). "In our research, increased expression of IL23A was observed in both TNBC cells treated with chemotherapeutic drugs and resected tumor tissues from patients who underwent neoadjuvant chemotherapy." (PMID 38902343, 2024). "The peritumoral administration of LL-37 significantly increased the expression of CXCL5, IL23A, MMP1a, and MMP9 mRNA in the tumor microenvironment." (PMID 36980564, 2023). "On the other hand, the factors uniquely enriched in GEC (IL23A and WNT16B) and GPC (IL33 and SEMA7A) significantly promoted proliferation of radiated (8 Gy mC-) tumor cells only." (PMID 36261421, 2022). "The results indicate that the mean HSCORES of FGF18, IL23A, and LIF in tumor tissues were significantly higher than those in normal tissues (p < 0.05), while the opposite trend was observed for SLIT2." (PMID 34017356, 2021). "In addition, monocytes (Hp+ and Ccl7+ monocytes) and conventional type 2 DCs (cDC2s) contributed to the total Il23a expression in the TME, with only negligible amounts in tumor-infiltrating T cells (TILs)." (PMID 38356059, 2024). "Among the most overexpressed genes in tumor cells compared to normal tissue were the transcription factors HOXB9, SIM2, ZIC5, SP8, TFAP2A, FOXE1, HOXB13, and SALL4; the cancer testis antigen CT83; and the cytokine IL23A." (PMID 37228492, 2023). "We generated IL-23A-expressing vvDD-IL-23A (identified by PCR amplification of il-23a cDNA from viral DNA; data not shown) and measured its expression in tumor cells in vitro." (PMID 34093846, 2021). "In addition, at the protein level, FGF18, IL23A, LIF, and VGF stained more deeply in tumor tissues than in normal tissues, while CCL28 and SLIT2 were only deeply stained in normal intestinal mucosal tissues according to the Human Protein Atlas." (PMID 34017356, 2021). "Acid-induced NF-κB activation downstream promotes the secretion of several cytokines, chemokines, and growth factors (IL1a, IL1b, IL6, IL8, IL23a, CCL5, CCL7, CXCL2, GM-CSF, and G-CSF) that can elicit local cancer aggressiveness, tumor immune escape, and tumor-induced nociception and hyperalgesia." (PMID 30825056, 2019). "Among the most overexpressed genes in tumor cells compared to normal tissue are genes coding for transcription factors (HOXB9, SIM2, ZIC5, SP8, TFAP2A, FOXE1, HOXB13, and SALL4), cancer testis antigens (CT83), and cytokines activating regulatory Th17 cells (IL23A)." (PMID 37228492, 2023). "It is worth mentioning that IL-23A may have pro-tumor activity that is not appreciated in the context of a replicating virus delivery." (PMID 34093846, 2021).
cancer (25 papers, 2012 to 2025). A tumor composed of atypical neoplastic, often pleomorphic cells that invade other tissues. "In the Cancer Cell Line Encyclopedia database, IL23A and LIF were found to be highly expressed in CRC cell lines." (PMID 34017356, 2021). "The effects of the M2-like phenotype have been more closely linked to cancer progression and metastasis and therefore patient prognosis with SPINK1, LAMC2, IGFBP1, and IL-23A gene expression." (PMID 34732817, 2021). "IL-23A was secreted from both macrophages and GC cells and promoted cancer proliferation through IL-17A/IL-17RA/NF-κB signaling." (PMID 25349535, 2014). "Although it was undetectable in the normal gastric glands and slightly positive in infiltrating inflammatory cells, IL-23A was detected at a high level in infiltrating inflammatory cells and cancer cells in cancer tissues." (PMID 25349535, 2014). "Indeed, we found that miR-146a over-expression reduced expression of several cytokines and growth factors with a known role in cancer development; IL-8, IL-23A, CCL5, CSF-1 and PDGFB." (PMID 22992343, 2012). "The genes validated in this study – PTGS2, IL8, IL23A, TACC2 and PI3 – were selected based upon their differential response to treatment and their implication for cancer initiation." (PMID 24848801, 2014). "Our results also indicated that IL-23A had no direct effect on the proliferation of cancer cells." (PMID 25349535, 2014).
inflammation (7 papers, 2011 to 2021). Aberrant reaction of the microcirculation characterized by movement of fluid and leukocytes from the blood into extravascular tissues. "Increased expression of the IL-23A subunit results in multi-organ inflammation, including intestinal inflammation." (PMID 23469228, 2013).
bacterial infection (4 papers, 2016 to 2020). "Many of the highly expressed genes encode important factors of the innate immunity such as IL-1A, IL-6, IL-23A, TNF superfamily proteins, CCL and CXCL chemokine families and NFκB and STAT4 regulators and belong to common expression pattern mounted by host cells upon bacterial infection." (PMID 32070192, 2020).
immune disease (2 papers, 2011 to 2021). "It is considered to be a T cell-dependent immune disease whose pathogenesis is influenced by cytokines, such as IL-10, IL-17A, IL-17RA, IL-23A and IL-23R." (PMID 34945130, 2021).
adenocarcinoma (1 paper, 2024). A common cancer characterized by the presence of malignant glandular cells. "Inasmuch as TNFα-NFκB pathway was enriched in KEAP1 R320 and R470 adenocarcinoma samples in our GSEA analysis, we analyzed the expression of two NFκB target genes, IL23A and BIRC2, in transduced cells." (PMID 38184997, 2024).
metabolic disorders (1 paper, 2017). "The use of complementary cross-enrichment analysis tools (Set Distiller and String) can be applied to extract useful functional insights or links of genes such as IL-17C and IL-23A that are important in the pro-inflammatory response of immunity and autoimmune or metabolic disorders." (PMID 28099447, 2017).
IL23A also shares sentences with these, for which no sentence is quoted: rheumatoid arthritis (16 papers); plaque psoriasis (6); ulcerative colitis (6); lupus (5); atopic dermatitis (4); diabetes (4); multiple sclerosis (4); adenoma (3); experimental autoimmune encephalomyelitis (3); pulmonary fibrosis (3); allergic aspergillosis (2); allergic disease (2); aneurysm (2); ankylosing spondylitis (2); disseminated candidiasis (2); enthesitis (2); fibrosarcoma (2); gastric cancer (2); giant cell arteritis (2); inflammatory skin disease (2); influenza (2); intestinal inflammation (2); lung carcinoma (2); nephritis (2); Obesity (2); ovarian carcinoma (2); palmoplantar pustulosis (2); SAPHO syndrome (2); Achalasia (1); acne (1).
A further 73 diseases each share a sentence with IL23A in 1 paper.